GLA (galactosidase alpha)
Diseases named in the same sentence as GLA in open-access papers (continued):
Sharing a sentence is not in itself a finding about the gene and the disease.
atherosclerosis (2 papers, 2010 to 2024). A disease characterized by the build-up of fatty material and calcium deposition in the arterial wall resulting in partial or complete occlusion of the arterial lumen. "The present case showed a clinical course of renal damage due to atherosclerosis and a better renal prognosis than case 6, which had been untreated for 30 years despite similar GLA activity and lyso-Gb3 levels in plasma (In case 6, serum creatinine was 4–5 mg/dL at age 50)." (PMID 38903807, 2024).
breast carcinoma (2 papers, 2014 to 2025). "Furthermore, we observed that bisecting GlcNAc modification inhibits breast cancer progression by promoting the degradation of α-galactosidase A (GLA)." (PMID 39851531, 2025). "Notably, GLA is highly expressed in several cancers, including breast cancer." (PMID 39851531, 2025). "In this study, we found that GLA knockdown suppressed proliferation and migration while promoting apoptosis in MDA-MB-231 cells, indicating that bisecting GlcNAc modification inhibits breast cancer progression by promoting GLA degradation." (PMID 39851531, 2025). "To investigate the role of GLA in breast cancer cells, we constructed MDA-MB-231 cell lines with stable GLA knockdown using shRNA lentivirus and found that GLA knockdown significantly suppressed cell proliferation in both CCK-8 and EdU assay, reduced cell migration, and promoted apoptosis." (PMID 39851531, 2025).
endothelial dysfunction (2 papers, 2012 to 2019). In vascular diseases, endothelial dysfunction is a systemic pathological state of the endothelium (the inner lining of blood vessels) and can be broadly defined as an imbalance between vasodilating and vasoconstricting substances produced by (or acting on) the endothelium. "We have previously published that endothelial dysfunction in the aorta is evident in 3–5 month-old GLA deficient compared to WT mice, characterized by decreased maximal vasodilation to ACh in the aorta (Emax: ~60%)." (PMID 31120949, 2019). "While GLA deficiency was always considered as the fulcrum of the disease, recent attention shifted towards studying the mechanisms through which Gb3 accumulation in vascular cells leads to endothelial dysfunction and eventually multiorgan failure." (PMID 22558451, 2012). "Taken together, these data indicate that our exercise intervention does not reverse endothelial dysfunction and oxidative stress level in these aged GLA-deficient mice." (PMID 31120949, 2019). "To date, the relative importance of Gb3 accumulation versus GLA deficiency in causing endothelial dysfunction is not fully understood; furthermore, its differential effects on cardiac micro- and macrovascular endothelial cells are not known." (PMID 22558451, 2012). "However, COX-1 and COX-2 appear to contribute to the vasculopathy in different ways, e.g., specific inhibition of COX-1 improved endothelium-dependent relaxation in aortas from GLA knockout mice, whereas COX-2 inhibition exacerbated the endothelial dysfunction." (PMID 22558451, 2012).
gastric cancer (2 papers, 2024 to 2025). A primary or metastatic malignant neoplasm involving the stomach. "This research explores the prognostic signature of MAGED2, KEAP1, GLA, EIF1AD, and EHF genes associated with hypoxia in gastric cancer through analyzing transcriptome information and scRNA-seq data, and indicates the clinical relevance of hypoxia during gastric cancer progression." (PMID 40129974, 2025).
glycogen storage disease (2 papers, 2018 to 2023). "We first focused on an estimation of enzymatic activities of lysosomal hydrolases encoded by genes causing the mucopolysaccharidosis (IDUA) and sphingolipidoses (GCase, ASMase, GALC, GLA) and additional glycogen storage disorders (glycogenosis) (GAA) in patients with late-onset SCZ." (PMID 38248833, 2023).
kidney damage (2 papers, 2020 to 2022). "In these cases, an appropriate genotype–phenotype correlation analysis is necessary so as not to attribute treatment failure to patients who are not going to develop kidney damage due to FD, such as patients with late-onset cardiac phenotypes or benign GLA gene variants carriers." (PMID 36292636, 2022).
Niemann-Pick disease, type C1 (2 papers, 2017 to 2024). Type C Niemann-Pick disease associated with a mutation in the gene NPC1, encoding Niemann-Pick C1 protein. "These were the genes encoding for Galactosidase A (GLA), Scavenger receptor class B member 2 (SCARB2), Niemann-Pick disease, type C1 (NPC1) and the CD164 molecule (CD164)." (PMID 29238336, 2017).
ovarian carcinoma (2 papers, 2014 to 2018). A malignant neoplasm originating from the surface ovarian epithelium. "We constructed a three-gene prognostic signature consisting of TXNRD1, GLA and GSTZ1 which was associated with overall survival for ovarian cancer patients received platinum-based chemotherapy, especially in those with elder age, high pathological grade and advanced tumor stage." (PMID 29910195, 2018). "In the present study, we, for the first time, identified a panel of three oxidative stress-related genes, including TXNRD1, GLA and GSTZ1, to predict overall survival for ovarian cancer patients." (PMID 29910195, 2018). "One branch clustered eight genes (NAGA, B4GALT6, HEXA, GLB1, GBA, GLA, UGCG, HEXB) with generally comparable expression levels among the cell lines, except for the UGCG gene which was expressed at considerably higher levels in both HOSE cell lines compared with the ovarian cancer cell lines." (PMID 25294702, 2014).
Adult onset (1 paper, 2024). Onset of disease manifestations in adulthood, defined here as at the age of 16 years or later. "The commonest genes affected in adult-onset FSGS (COL4A3–COL4A5,GLA ) have ocular abnormalities but not the other frequently affected genes (ACTN4, CD2AP, INF2, TRPC6)." (PMID 37578539, 2024).
Age-related cataract (1 paper, 2024). A type of cataract (opacification of the lens) that forms during the course of aging. "Implications for future research and clinical applications may include alternative treatment of age-related cataract such as solid lipid nanoparticles to target certain proteins, like GLA and ST3GAL5, in order to slow down or even prevent age-related cataract progression." (PMID 39685745, 2024).
atopic dermatitis (1 paper, 2017). "In particular, DGLA, GLA, which has anti-allergic effects, such as for atopic dermatitis in NC/Nga mice and humans, suppressed clinical severity of skin lesions." (PMID 29143798, 2017).
Cerebral ischemia (1 paper, 2013). Restriction of arterial blood supply to the brain associated with insufficient oxygenation to support the metabolic requirements of the tissue. "In this respect, a recent prospective study including 625 patients with cerebral ischemia aged between 18 and 55 reported that GLA D313Y was associated with cryptogenic stroke." (PMID 23393592, 2013).
cerebral small vessel disease (1 paper, 2021). Cerebral small vessel disease is the term currently used to pathological processes that affect the brain parenchymal circulation (arterioles, capillaries, and veins). "For patients carrying variants outside EGFr region, no potential pathogenic mutation were identified in several other genes known to be common causal of cerebral small-vessel disease or vascular dementia (HTRA1, TREX1, COL4A1, COL4A2, GLA, APP, and ITM2B) by targeted next-generation sequencing." (PMID 34335700, 2021).
developmental disability (1 paper, 2022). Disorders in which there is a delay in development based on that expected for a given age level or stage of development. "Family screening revealed the same GLA gene mutation in his 41-year-old daughter, without clinical manifestations of the disease, and in her 11-year-old son, who presented with developmental disability." (PMID 35548424, 2022).
Dyskinesia (1 paper, 2022). A movement disorder which consists of effects including diminished voluntary movements and the presence of involuntary movements. "All GLA p.Asp313Tyr positive subjects had a good response to dopaminergic medication, and all of them developed fluctuations and dyskinesia at the time of clinical assessment." (PMID 35111290, 2022).
Ebola (1 paper, 2021). "Regarding the adjuvant, we previously showed that GLA-SE adjuvanted FILORAB1 rabies virus-based EBOLA vaccine, protected 100% of NHPs challenged with Ebola, an improvement from the unadjuvanted FILORAB1 vaccine, which was less protective." (PMID 33765062, 2021).
Fibroadenoma (1 paper, 2020). A benign tumor of the breast characterized by the presence of stromal and epithelial elements. "For fibroadenoma tissues, compared with both fibroadenoma-adjacent and normal tissues, there were six up-regulated (ANXA6, VCP, SERPINH1, galactosidase alpha, NNT, and MMP11) and 38 down-regulated (KRT10, KRT1, ALDH1A1, ECM1, and others) proteins in fibroadenoma." (PMID 33194682, 2020). "We detected an increase in the expression of six proteins (NUDT19, FBN1, NONO, FLNA, SCPEP1, and galactosidase alpha) in fibroadenoma." (PMID 33194682, 2020).
fungal infection (1 paper, 2017). "Our results show that C. albicans and A. fumigatus induce a significantly higher expression of the GLA gene than E. coli, suggesting the importance of this enzyme in monocytes during fungal infection." (PMID 29238336, 2017).
lymphatic disorders (1 paper, 2019). "CLAs are intractable lymphatic disorders, and include GLA, GSD, KLA, and CCLA." (PMID 31236308, 2019).
multiple sclerosis (1 paper, 2019). A progressive autoimmune disorder affecting the central nervous system resulting in demyelination. "Recent studies on α-galactosidase A (GLA) deficiency, causing Fabry disease, an X-linked disorder causing systemic symptoms, have suggested a possible association between GLA mutations and PD or multiple sclerosis." (PMID 31284408, 2019).
multiple system atrophy (1 paper, 2023). Multiple system atrophy (MSA) is a neurodegenerative disorder characterized by autonomic failure (cardiovascular and/or urinary), parkinsonism, cerebellar impairment and corticospinal signs with a median survival of 6-9 years. "Interestingly, elevated GLA activity in the blood was reported in LRRK2-PD patients and patients with one of the forms of synucleinopathies (multiple system atrophy)." (PMID 36901867, 2023). "Previously, we showed increased GLA expression levels and activity in the blood of patients with multiple system atrophy but not in PD." (PMID 36901867, 2023).
nephrotic syndrome (1 paper, 2024). A collection of symptoms that include severe edema, proteinuria, and hypoalbuminemia; it is indicative of renal dysfunction. "The second patient who carried the GLA gene c.937G>T, (p.Asp313Tyr) variant was a 56 year-old female with nephrotic syndrome who underwent a kidney biopsy when she was 45 years-old." (PMID 38338714, 2024).
polycystic kidney disease (1 paper, 2022). A usually autosomal dominant and less frequently autosomal recessive genetic disorder characterized by the presence of numerous cysts in the kidneys leading to end-stage renal failure. "We report a patient with Fabry with the classic c.730G > A (p.Asp244Asn) variant of the GLA gene and large complex renal cysts identified as co-existing polycystic kidney disease." (PMID 36406818, 2022).
sarcopenia (1 paper, 2021). Progressive decline in muscle mass due to aging which results in decreased functional capacity of muscles. "Dephosphorylated, uncarboxylated Matrix-GLA-protein presented only at the lowest tertile (representing high vitamin K levels); significant associations with sarcopenia defined by AMMI, LESMI and rLM20, indicated a vitamin K independent pathway." (PMID 35011061, 2021).
uveal melanoma (1 paper, 2023). A melanoma derived from melanocytes of the uveal tract. "It was found that OS of patients with adrenocortical carcinoma (ACC) (P<0.001), liver hepatocellular carcinoma (LIHC) (P=0.015) and uveal melanoma (UVM) (P=0.001) was obviously shorter in GLA overexpression group than in the GLA downexpression group." (PMID 37057282, 2023).
tumor (15 papers, 2012 to 2025). "Furthermore, patients with higher expressions of VPS35 and HIF-1α frequently associated with larger tumor size; while higher expression of GLA was indicative of worse T stage, N stage and AJCC stage." (PMID 38528532, 2024). "Altering cytokine profiles within the TME, GlA shifts the balance from anti-inflammatory to pro-inflammatory cytokines, promoting a Th1 immune response conducive to tumor rejection." (PMID 38338469, 2024). "Secondly, further in vitro and in vivo studies are needed to validate GLA's role in LGG tumor immune infiltration." (PMID 37057282, 2023). "Glaucocalyxin A, denoted as GLA, has been recognized for its tumor-suppressive capacities across a gamut of malignancies." (PMID 38075693, 2023). "The results of IHC demonstrated that the expression of CDC37, GLA, HIF-1α and VPS35 was upregulated in the tumor tissues compared with corresponding normal tissues." (PMID 38528532, 2024). "Together, this suggested the expression of GLA in LGG may be more predictive of immune infiltration, with potential value for assessment of tumor development." (PMID 37057282, 2023). "GLA and DGLA could also induce T-regulatory cell activity, e.g., transforming growth factor (TGF)-beta-producing T cells, and reduce proinflammatory interleukin (IL)-1 and tumor necrosis factor (TNF)-alpha production, indicating immunity mechanism is likely to participate in the anti-tumor effect." (PMID 22333072, 2012).
cancer (10 papers, 2017 to 2025). A tumor composed of atypical neoplastic, often pleomorphic cells that invade other tissues. "Additionally, Fabry patients, caused by mutations in the GLA gene, exhibit a slightly reduced cancer rate." (PMID 39851531, 2025). "GLA has been shown to exhibit anti-proliferative activities specifically in a variety of cancer cell lines both in vitro and in vivo." (PMID 33446783, 2021). "Most of these genes, such as CDIPT, PIK3C2G, ARSJ, ARSE, GLA and GLB2, had not been studied in cancers." (PMID 31475440, 2019).
kidney disease (8 papers, 2010 to 2026). "With regard to the low lyso-Gb3 levels, as well as atypical disease course, in a 68-year-old patient with renal disease, a novel variant c.895G>C (p.D299H) was also referred to the mild variant of the GLA gene." (PMID 38002959, 2023).
peripheral neuropathy (7 papers, 2017 to 2023). A disorder affecting the peripheral nervous system. "For example, in a study of patients with small-fibre neuropathy, 5/24 (20.8%) were found to have GLA mutations." (PMID 28871487, 2017). "Finally, the wide range of intrafamilial phenotypic variability regarding the severity of the disease but also the affected target-organs in patients with the same GLA mutation should also be considered analysing the peripheral neuropathy in FD." (PMID 28672034, 2017). "Three of the 4 other peripheral neuropathy-related genes (PMP22, KIF1B, GLA) also have shown to contribute to aberrant mitochondrial dynamics, axonal transport, and/or mitophagy." (PMID 37234784, 2023).
metabolic disease (6 papers, 2012 to 2025). A congenital disorder (due to inherited enzyme abnormality) or acquired (due to failure of a metabolically important organ) disorder resulting from an abnormal metabolic process. "Most of these P/LP variants were found in validated minor sarcomere genes (ACTC1, MYL2 and MYL3) and genes related to metabolic diseases (GLA and PRKAG2)." (PMID 28771489, 2017). "Fabry’s disease (FD) is an inherited metabolic disease that results from lack of the enzyme α-galactosidase due to GLA gene mutation." (PMID 36295831, 2022).
infection (5 papers, 2011 to 2025). The state of being infected such as from the introduction of a foreign agent such as serum, vaccine, antigenic substance or organism. "Similar to previous studies, the antigen-specific Th1/Th17 responses generated herein were enhanced by CFA+GLA-SE/CDG immunization and maintained at 10 weeks post-infection, resulting in decreases in the bacterial loads and lung inflammation, and consequently slowed the progression of MAC-PI." (PMID 35499090, 2022).
cardiac disease (4 papers, 2014 to 2026). "This point of view is supported by facts such as increased substrate concentration in urine in ~ 15% of patients with heart diseases without any mutations in the GLA gene." (PMID 35578305, 2022).
vasculopathy (4 papers, 2012 to 2025). "This approach also enabled efficient recapitulation of Fabry nephropathy with vasculopathy using GLA-knockout hPSCs, and, upon transplantation into mouse kidney, promoted endothelial cell recruitment from the host and maintained vascular integrity with more organized slit diaphragm-like structures." (PMID 40989835, 2025). "Differentiation of α‐galactosidase A (GLA)‐knock‐out hPSCs generated using CRISPR/Cas9 into kidney organoids by the culture method using kidney dECM efficiently recapitulate Fabry nephropathy with vasculopathy." (PMID 35322595, 2022). "Deregulation of key endothelial pathways as observed in FD vasculopathy is likely caused by intracellular Gb3 accumulation rather than deficiency of GLA." (PMID 22558451, 2012). "We conclude herewith that vasculopathy in FD is directly caused by intracellular Gb3 accumulation primarily in microvascular endothelial cells, while deficiency of GLA alone does not cause any deregulation of key vasoactive mediators." (PMID 22558451, 2012).
cardiovascular disease (3 papers, 2019 to 2023). "The phenotype of FD results from variants on the GLA gene which codes for α-Gal A production, and variants on this gene have been shown to be strongly related to unexplained or idiopathic cardiovascular disorders." (PMID 32292674, 2020).
kidney (1 paper, 2020). "Notably, this was the first study identifying pathogenic mutations of GLA gene in female kidney transplant recipients." (PMID 33036343, 2020).
GLA also shares sentences with these, for which no sentence is quoted: genetic disorder (11 papers); Gaucher disease (10); Lysosomal disease (7); asthma (4); focal segmental glomerulosclerosis (4); heart failure (4); Parkinson disease (4); end-stage renal disease (3); gastrointestinal disorders (3); Hypertension (3); influenza (3); Krabbe disease (3); allergic reaction (2); Arrhythmia (2); CARASIL (2); Dent disease (2); hepatorenal syndrome (2); Leukoencephalopathy (2); lung carcinoma (2); Tay-Sachs disease (2); transient ischemic attack (2); Ventricular hypertrophy (2); amyloidosis (1); Anosmia (1); aortic aneurysm (1); arrhythmogenic right ventricular cardiomyopathy (1); atypical hemolytic-uremic syndrome (1); autoimmune disease (1); autonomic dysfunction (1); autosomal-dominant tubulointerstitial kidney disease (1).
A further 95 diseases each share a sentence with GLA in 1 paper.